RN7SL649P (RNA, 7SL, cytoplasmic 649, pseudogene)
Gene: Miscellaneous RNA gene on chromosome 1 (12,036,740 to 12,037,014, reverse strand). Ensembl gene ENSG00000243539.
Homologues: Orthologues: chimpanzee Metazoa_SRP (99% identical). Paralogues in human: RN7SL1 (81% identical), RN7SL2 (81% identical), RN7SL3 (81% identical), RN7SL220P (80% identical), RN7SL664P (80% identical), RN7SL20P (80% identical), RN7SL126P (80% identical), RN7SL122P (79% identical), RN7SL408P (79% identical), RN7SL416P (79% identical), RN7SL45P (79% identical), RN7SL464P (79% identical), and 698 more.